EPCAM (epithelial cell adhesion molecule)
Description:
May act as a physical homophilic interaction molecule between intestinal epithelial cells (IECs) and intraepithelial lymphocytes (IELs) at the mucosal epithelium for providing immunological barrier as a first line of defense against mucosal infection. Plays a role in embryonic stem cells proliferation and differentiation. Up-regulates the expression of FABP5, MYC and cyclins A and E.
Synonyms: Ep-CAM; EGP314; CD326; GA733-2; M4S1; MIC18; TACSTD1; TROP1; Ly74; EGP34; EGP40; EGP-2; KSA; HEA125; KS1/4; MK-1; MH99; MOC31; MOC-31; 323/A3; and 9 more
Tractability: Small molecule: a structure with a bound ligand is known. Antibody: an approved drug acts on it; UniProt places it where antibodies can reach, with high confidence; its Gene Ontology location is reachable by antibodies, with high confidence; UniProt predicts a signal peptide or a membrane-spanning region; the Human Protein Atlas places it where antibodies can reach. PROTAC: ubiquitination databases record sites on it. Other modalities: a drug acting on it is in phase 2 or 3 trials.
Target class: Adhesion
Gene: Protein-coding gene on chromosome 2 (47,345,158 to 47,387,601, forward strand). Ensembl gene ENSG00000119888.
Subcellular location: Lateral cell membrane; Cell junction, tight junction
Subcellular location (Human Protein Atlas): Plasma membrane
Pathways (Reactome):
Developmental Biology: Developmental Lineage of Mammary Gland Alveolar Cells; Developmental Lineage of Mammary Gland Luminal Epithelial Cells; Developmental Lineage of Mammary Gland Myoepithelial Cells; Developmental Lineage of Mammary Stem Cells
Disease: Attachment of bacteria to epithelial cells
Hemostasis: Cell surface interactions at the vascular wall
Gene Ontology:
Molecular function: protein binding; protein-containing complex binding; cadherin binding involved in cell-cell adhesion
Biological process: negative regulation of cell-cell adhesion mediated by cadherin; positive regulation of cell population proliferation; positive regulation of stem cell proliferation; positive regulation of transcription by RNA polymerase II; signal transduction involved in regulation of gene expression; stem cell differentiation; cell-cell adhesion; ureteric bud development
Cellular component: apical plasma membrane; basolateral plasma membrane; bicellular tight junction; extracellular exosome; lateral plasma membrane; plasma membrane; cell surface; membrane
Genetic constraint (gnomAD): Loss-of-function variants: 17 observed, 19.01 expected, observed/expected ratio (o/e) 0.89, 90% interval 0.61 to 1.34. The upper end of that interval is the gene's LOEUF score, 1.34, which puts it in group 5 of 6, group 1 being the genes least tolerant of losing a copy. Missense variants: 351 observed, 263.69 expected, observed/expected ratio (o/e) 1.33, 90% interval 1.22 to 1.45. Synonymous variants: 123 observed, 97.51 expected, observed/expected ratio (o/e) 1.26, 90% interval 1.09 to 1.47.
Gene-disease validity (ClinGen):
ClinGen rates the evidence that EPCAM causes each of these diseases.
Lynch syndrome (autosomal dominant): Definitive. An autosomal dominant hereditary neoplastic syndrome characterized by the development of colorectal carcinoma and a high risk of developing endometrial carcinoma, gastric carcinoma, ovarian carcinoma, renal pelvis carcinoma, and small intestinal carcinoma.
hereditary breast carcinoma (autosomal dominant): Refuted. Breast carcinoma that has developed in relatives of patients with history of breast carcinoma.
Homologues: Orthologues: macaque EPCAM (94% identical), chimpanzee EPCAM (92% identical), rabbit EPCAM (82% identical), mouse Epcam (82% identical), rat Epcam (79% identical), pig EPCAM (77% identical), dog EPCAM (73% identical), guinea pig EPCAM (71% identical), tropical clawed frog epcam (48% identical), zebrafish epcam (38% identical). Paralogues in human: TACSTD2 (50% identical).
Diseases named in the same sentence as EPCAM in open-access papers:
EPCAM is named in the same sentence as 416 diseases in open-access papers, as found by Europe PMC text mining. Sharing a sentence is not in itself a finding about the gene and the disease. The quoted sentences say what the papers report.
breast carcinoma (641 papers, 2003 to 2026). "EpCAM is employed as the primary discriminating diagnostic marker in breast cancers, and decades of study have confirmed its salience in predicting overall survival and progression-free survival heterogeneity." (PMID 40867346, 2025). "Perhaps the association of EpCAM overexpression with poor prognosis in breast cancer is largely due to CD133 expression." (PMID 39456890, 2024). "Breast cancer has been shown to belong to a group of carcinomas in which EpCAM overexpression is associated with an unfavorable disease course and outcome." (PMID 39456890, 2024). "Research investigations have revealed a strong association between EpCAM and drug resistance across multiple cancer types, including ovarian cancer, breast cancer, and leukemia." (PMID 38187284, 2024). "Next, we focused on the protein expression levels of Itgav, Itgb3, and Vcam1, as they exhibited a progressive increase during mouse cSCC progression and had previously been associated with different EMT transition states in EpCAM− skin and breast cancer cells." (PMID 39075581, 2024). "In breast cancer, elevated EpCAM expression was also tightly linked to key molecular features such as the loss of ER and PR expression as well as HER2 overexpression in our study." (PMID 38786342, 2024). "EpCAM is a tumor-associated antigen that has been identified as a marker for most epithelial malignancies, including breast cancer." (PMID 37670250, 2023). "ROR1-lEVs correlated with EpCAM-lEVs, which have already been established as prognostic and diagnostic biomarkers for breast cancer." (PMID 37430307, 2023). "In a previous study, we have demonstrated that EpCAM, a glycosylation protein, is associated with cell growth and metastasis in breast cancer." (PMID 34983878, 2022). "In this study, breast cancer cells were transfected with N-glycosylation mutation EpCAM plasmid to express deglycosylated EpCAM." (PMID 34983878, 2022). "The EpCAM molecule is also often expressed inhuman breast cancer cells, which is associated with a poor prognosis." (PMID 35441046, 2022). "The epithelial cell adhesion molecule (EpCAM) was implicated in tumor progression and drug resistance in breast cancer." (PMID 36315446, 2022). "Taken together, it demonstrated that in breast cancer cells autophagy is associated with glycosylation of EpCAM." (PMID 34983878, 2022). "In summary, we reported the autophagy disorder induced by three glycosylation point mutations in EpCAM in breast cancer cells." (PMID 34983878, 2022). "EpCAM protein is a potential target associated with breast-cancer cell proliferation, invasion, and metastases." (PMID 35877345, 2022). "Previously, it was demonstrated that overexpression of EpCAM in breast cancer caused tumor relapses, metastatic progression and poor survival." (PMID 36045404, 2022). "In breast cancer, loss of EpCAM expression in CTCs served as a marker of chemotherapy resistance, while another study showed increased EpCAM expression in treatment resistant patients." (PMID 34209658, 2021). "Pathological changes associated with EMT have not usually been observed in lobular breast cancer and it remains uncertain what is the cause of lower EpCAM expression in this breast cancer subtype." (PMID 34209658, 2021). "The CellSearch® technique is limited by the lack of CTC detection during EMT, but this factor does not seem to constitute a limitation for tumors in which the presence of EpCAM is strongly associated with tumor progression, such as breast cancer." (PMID 34644733, 2021). "They found EPCAM-negative and EPCAM low expression in breast cancer CTCs, underlining the weakness of EPCAM-based isolation methods." (PMID 33081135, 2020). "We report here a combined anti-cancer therapy directed toward HER2 and EpCAM, common tumor-associated antigens of breast cancer cells." (PMID 33081407, 2020).
breast carcinoma (continued). "EpCAM expression was associated with cell adhesion, and N-glycosylation mutation of EpCAM decreased adhesion capacity in breast cancer cells." (PMID 32046162, 2020). "Initial characterization of EpCAM functions was conducted in murine fibroblasts and L153S mammary carcinoma cells, which are characterized by loss of cell adhesion and the adoption of a spindle-shaped morphology." (PMID 32507912, 2020). "EpCAM is found in breast cancer circulating tumor cells and it has been associated with cancer cell proliferation, survival, migration, invasion, and enhanced bone metastases’ formation." (PMID 33182375, 2020). "EpCAM expression is also associated with cancer stem cell-like phenotypes in breast cancer that contribute to the formation of bone metastasis." (PMID 32764280, 2020). "In breast cancer for instance, EpCAM is associated with an unfavorable prognosis in the luminal and basal-like intrinsic subtypes but with a favorable prognosis in the HER2 intrinsic subtype." (PMID 31225512, 2019). "In this study, we directly compared PIK3CA hotspot mutations (E545K, H1047R) in EpCAM‐positive CTCs and paired plasma‐ctDNA in breast cancer (BrCa)." (PMID 31254443, 2019). "EMT-associated markers EGFR, EpCAM, fibronectin and vimentin were also evaluated using immunofluorescence for the six breast cancer cell lines." (PMID 31430931, 2019). "Because of their exquisite affinity and specificity, the anti-EpCAM aptamers discriminated breast cancer xenograft tissues, in tissue staining experiments with fluorescently labeled aptamers, depending on the expression level of EpCAM on cell surface." (PMID 30428522, 2018). "EpCAM expression, associated with lower survival rates, has been described in patients with breast cancer, ovarian cancer, gallbladder cancer, and clear cell renal tumors." (PMID 30112355, 2018). "Lower expression of CD24, CD44, ALDH1 and EpCAM is linked with better prognosis of breast carcinoma in patients." (PMID 28524540, 2017). "The second paper published in 2015 described the use of an EpCAM aptamer linked to a PlK-1 siRNA for the treatment of breast cancer." (PMID 28792479, 2017). "EpCAM is highly over-expressed in primary and metastatic breast cancer and associated with poor disease-free and overall survival in primary breast cancers." (PMID 26984381, 2016). "Here, we present evidence that Gal3 expression is linked to an epithelial phenotype (EpCAM+ and E-cadherin+), lower drug resistance, and decreased tumorigenicity in human breast cancer cells." (PMID 27687248, 2016). "The quantitative evaluation of circulating EpCAM+ tumor cells (CTCs) in the peripheral blood of breast cancer patients provides an independent predictor of risk of progression in patients with metastatic disease." (PMID 28721373, 2016). "EpCAM overexpression has been represented to be associated with a strongly invasive and aggressive cancer phenotype in breast cancer." (PMID 27886058, 2016). "EpCAM is associated with increased proliferation, migration and invasion in both breast cancer and RB.EpCAM protein is differentiated into extracellular domain (EpEx), transmembrane domain (EpTM) and intracellular domain (EpICD)." (PMID 26176230, 2015). "EpCAM is commonly expressed in breast cancer, and EpCAM expression in primary breast cancers is associated with a poor prognosis." (PMID 26356670, 2015). "E-cadherin is an epithelial cell adhesion molecule which is known to play key role in initial stage of metastasis and has been associated with poorly invasive and poorly differentiated breast cancer phenotype." (PMID 24489904, 2014). "For example, EpCAM expression correlated with an unfavourable outcome in patients suffering from basal-like and luminal breast cancer subtypes, while high-level EpCAM expression was associated with enhanced overall survival in the HER2 subtype." (PMID 24009667, 2013).
breast carcinoma (continued). "We also found an exon 10 BRCA2 variant (N372H; OMIM_ID # 600185.0133), and an EPCAM variant identified in Chinese population (M143T; rs1126497;) that are associated with increased risk for breast cancer." (PMID 22938532, 2012). "In this study we confirm that EpCAM expression is associated with increased breast cancer invasion in vitro and in vivo." (PMID 22132731, 2011). "To address the potential mechanism(s) underlying the impact of EpCAM on breast cancer invasion, we used a luciferase reporter pathway profiling system to measure the activity of specific transcription factors following specific ablation of EpCAM expression." (PMID 22132731, 2011). "EpCAM overexpression has been reported to be associated with a strongly invasive and aggressive tumour phenotype in breast cancer." (PMID 21281469, 2011). "In the transfected, constitutively EpCAM-expressing human breast cancer cell lines described here, we observed a reduced expression of Wnt signaling associated components after EpCAM overexpression." (PMID 21281469, 2011). "For instance, EpCAM expression in primary breast cancers appears to be associated with decreased patient survival." (PMID 22132731, 2011). "We confirm that EpCAM expression is associated with increased breast cancer invasion in vitro and in vivo, and demonstrate for the first time that EpCAM expression is capable of modulating the JNK/AP-1 signal transduction pathway." (PMID 22132731, 2011). "In loss-of-function, and gain-of-function experiments we demonstrate that EpCAM expression is associated with increased breast cancer invasion in vitro and in vivo." (PMID 22132731, 2011). "Expression of EpCAM has previously been linked to poorer survival time in several tumour types including breast cancer, gallbladder tumours, and those of the Papilla Vateri." (PMID 20606680, 2010). "EpCAM overexpression is correlated with poor disease free suvival in breast cancer, and loss of EpCAM expression in gastric adenocarcinoma has been reported to be associated with poor TNM staging prognosis, although inconsistent." (PMID 17125516, 2006). "Studies have shown that epithelial cell adhesion molecule (EpCAM), as one of the key surface markers of breast cancer CSCs, induces the loss of E-cadherin and upregulates the expression of Vimentin and VE-cadherin by activating EMT-related transcription factors Slug, Twist1, and ZEB1." (PMID 41019994, 2025). "Based on the sandwich ELISA principle, isolated EVs were captured by anti-CD63 modified magnetic beads and subsequently bound by breast cancer-associated markers (EpCAM, PSMA, HER2, EGFR, CEA, CA125) serving as detection probes, with sensing completed via TMB oxidation-induced color change." (PMID 41404198, 2025). "We chose cancer markers CD24 and EpCAM due to their association with breast cancer." (PMID 39513819, 2024). "Our data supports previous data on breast cancer showing that the expression of PD-L1 was strongly associated with stem cell-like cells where the CSC population (EpCAM+CD44hiCD24lo) had a higher level of PD-L1 compared to their counterparts (EpCAMlo/negCD44loCD24hi)." (PMID 37686163, 2023). "PDBCCs were extracted from fresh surgical tumor tissues and cultured for 7–10 days in Matrigel on a culture plate before being coupled to collagen I-coated plates and flow cytometry analysis to identify EpCAM-positive breast cancer cells and fibroblast marker-positive cancer-associated fibroblasts." (PMID 37670250, 2023). "Several studies found that increased EpCAM expression was associated with advanced stage and poor survival in patients with breast cancer, gallbladder cancer, ovarian cancer, Vater tubercle and esophageal cancer, and oral squamous cell carcinoma, because it acts as an inhibitor of E-cadherin." (PMID 37627911, 2023).
breast carcinoma (continued). "Previous studies have demonstrated that overexpression of EpCAM is associated with poor prognosis in patients with esophageal squamous cell carcinoma, lung cancer, and breast cancer, and it can be used as a marker for circulating tumor cells involved in cancer cell metastasis." (PMID 35911706, 2022). "Moreover, the epithelial cell adhesion molecule (EpCAM) is associated with a hybrid epithelial–mesenchymal phenotype in breast cancer." (PMID 36139006, 2022). "For breast cancer‐specific survival, four markers were associated with OS in the tumor compartment (EpCAM, P = 0.0072; ER, P = 0.037; Ki‐67, P = 0.039; STING, P = 0.043) and four in the stromal compartment (CD8, P = 0.024; CD25, P = 0.013; CD56, P = 0.018; ER, P = 0.018)." (PMID 34018684, 2022). "It suggests that the plasma exosomal EpCAM might provide diagnostic assistance for non-invasive, early detection of breast cancer." (PMID 34073560, 2021). "Notably, while both EPCAM+ and EPCAM− CTCs were detected in metastatic prostate and breast cancer patients, only the EPCAM+ CTCs were associated with overall survival." (PMID 34206049, 2021). "In a clinical cohort of patients with stages III and IV metastatic breast cancers, by using EpCAM as a marker for EMT, the loss of epithelial phenotype in CTCs has been demonstrated, while bone marrow-derived disseminated tumor cells retained an epithelial phenotype." (PMID 34063272, 2021). "In addition, it has been suggested that ITGA6+/EpCAM+ mammary luminal progenitor cells were possible transformation targets in basal-like breast cancers, which have close associations with poor prognosis." (PMID 31340763, 2019). "In the previous cases (with and without treatments), we have considered that metastases in the bone are originated only by breast cancer cells with four driver mutations relative to four proteins EPCAM, CD44, CD47 and MET, and they correspond to four branching of the CTCs departing from the DLU." (PMID 25978366, 2015). "Although a previous study demonstrated that EpCAM knockdown is effective in the prevention of breast cancer invasion and metastasis, the direct cytotoxicity of EpCAM in breast cancer and the underlying mechanisms remain unclear." (PMID 25019346, 2014). "For example, rs17632542 in the KLK3 gene is implicated in high association to prostate cancer susceptibility, and rs1126497 with a C/T polymorphism in epithelial cell adhesion molecule (EpCAM) in its exon 3 has been linked to increased risk of breast cancer in chinese populations." (PMID 23656885, 2013). "EpCAM expression is associated with increased breast cancer invasion." (PMID 22132731, 2011). "However, the functional role of EpCAM in regulating cancer invasion remains controversial, and the mechanism(s) underlying EpCAM-mediated regulation of breast cancer invasion remain to be defined." (PMID 22132731, 2011). "An EpCAM-associated downregulation of inhibitory and repressor molecule expression might contribute to the activation or enhancement of Wnt signaling in breast cancer and therefore further corroborate the ongogenic potential of the EpCAM tumour antigen." (PMID 21281469, 2011). "Molecular therapies capable of interfering with EpCAM-mediated signaling may find particular success in the treatment of breast cancer, where EpCAM expression is associated with increased invasion and poor prognosis." (PMID 22132731, 2011). "Loss-of-function analyses using RNA interference suggest that EpCAM expression is associated with increased invasion in breast cancer, and gain-of-function analyses in colorectal and lung cancers suggest that EpCAM expression is associated with decreased cancer invasion in these cancer types." (PMID 22132731, 2011). "Notably, EpCAM is approved for diagnostic use in the CellSearch assay which aims to detect circulating breast cancer cells." (PMID 21816090, 2011). "In addition, the ability to secrete PGE2 associates with the ability to expand CD44+/CD24−/EpCAM+ breast cancer cells." (PMID 21957456, 2011).